WNT5A (Wnt family member 5A)
Diseases named in the same sentence as WNT5A in open-access papers (continued):
Sharing a sentence is not in itself a finding about the gene and the disease.
breast carcinoma (continued). "In particular, a Wnt5a mimicking peptide, Foxy-5, has been shown to be a promising agent to suppress metastasis of patients with prostate cancer or breast cancer with low endogenous expression of Wnt5a, but it did not affect those with higher endogenous levels of Wnt5a." (PMID 33654199, 2021). "Interestingly, Wnt5a-mediated BMI-1 upregulation in breast cancer cells was observed only at the protein level and not at the mRNA level, indicating that this process is not regulated via transcriptional activation." (PMID 31382410, 2019). "In good agreement with our assumption, it was demonstrated that treatment of WNT5A-lacking breast cancer cells with Foxy5 reduces the metastatic spread of breast cancer cells by 70–80% in an orthotopic mouse model, highlighting its therapeutic potential as an anti-metastatic drug candidate." (PMID 30171384, 2018). "Comparison of recurrence-free survival, for which 5-year survival rates were 81.1% and 100% in Wnt5a-positive and Wnt5a-negative breast cancers, respectively, revealed a significant difference according to statistical analysis using the log-rank test (P = 0.024)." (PMID 29765514, 2018). "Wnt5a was expressed in the cytoplasm but not the nucleus of breast cancer cells." (PMID 29765514, 2018). "Hence, we analyzed the expression of active (non-phosphorylated) β-catenin in the two WNT5A-expressing breast cancer cell lines." (PMID 29069720, 2017). "In addition to its effect on constitutive TLR3, Wnt5a levels and subsequent IL-6 production and STAT3 levels/activation, we then evaluated the ability of C10 to inhibit the migration and viability/growth of MCF-7 breast cancer cells." (PMID 29371911, 2017). "However, more lines of study suggested that activation of noncanonical Wnt signaling, such as the Wnt5a-mediated signaling, was aberrantly enhanced in many epithelial cancers, including the lung cancer, breast cancer, ovarian cancer, and gastric cancer." (PMID 27895670, 2016). "Since it is known that ROR1/2 signaling, especially after stimulation with Wnt5a, requires Dvl for signal transduction, we aimed to analyze which of the Dvl proteins (Dvl1, Dvl2 or Dvl3) might be a good marker for active ROR signaling in breast cancer." (PMID 26862065, 2016). "Given that nucleolar size and elevated levels of rRNA synthesis correlate with poor prognosis in breast cancer, we posit that non-canonical signaling of Wnt5a through DVL1 and the consequent reduction in rRNA synthesis contributes to the role of Wnt5a in tumor suppression." (PMID 27500936, 2016). "Furthermore, GPC6 promotes invasive migration of breast cancer cells through a noncanonical Wnt5A signaling pathway." (PMID 26448945, 2015). "Stimulation with recombinant Wnt-5a or the Wnt-5a mimicking hexapeptide Foxy5 did significantly decrease the invasive capacity of both ER-negative and ER-expressing cells, demonstrating that the ability of Wnt-5a signaling to impede breast cancer cell invasion is not affected by ER-status." (PMID 23990917, 2013). "The signaling cascade initiated by WNT5A that regulates migration in breast cancer is not clear and may be context specific." (PMID 23484019, 2013). "MDA-MB-231 and 4T1 breast cancer cells are highly metastatic and express little to no WNT5A." (PMID 23484019, 2013). "Interestingly, it has recently been demonstrated that WNT‐5A induced MMP9 mRNA expression through a ERK1/2 signaling mechanism in microglia, which appears contrary to our present findings on breast cancer cells." (PMID 23727359, 2013). "Interestingly, ERα expression was restored at both mRNA and protein level after treatment of ERα-negative breast cancer cells with Wnt-5a." (PMID 21629692, 2011). "Additionally, the WNT5A levels in the tumor samples did not correlate with proliferation markers or phosphorylation of the retinoblastoma protein (RB), indicating that the WNT5A protein is not involved in the proliferation of breast cancer." (PMID 30171384, 2018).
breast carcinoma (continued). "Furthermore, the WNT5A molecule is hydrophobic and has a heparin sulfate-binding domain important for its auto- and paracrine functions that make it less likely that the WNT5A molecule can be used for systemic treatment since it will not reach and target breast cancer cells." (PMID 30171384, 2018). "Therefore, it is possible that Wnt5a or Wnt16 may activate either the canonical or noncanonical Wnt signaling pathway in a receptor context-dependent manner in human breast cancer stem cells." (PMID 28491097, 2017). "Wnt5a-induced formation of mammospheres was not caused by an increase in canonical Wnt/β-catenin signaling, but was instead mediated by noncanonical Wnt signaling requiring the receptor tyrosine kinase ROR2 and the activity of the Jun N-terminal kinase, JNK, in mouse breast cancer cells." (PMID 28491097, 2017). "WNT5A/5B are ligands of the noncanonical Wnt signaling pathway, and WNT5A has previously been shown to play a critical role in maintaining HMLER cells, as well as the SUM159 breast cancer cell line, in a fully mesenchymal state." (PMID 38111531, 2023). "Other breast cancer cells reacted with the induction of different non-canonical WNT ligands, such as WNT5A in SK-BR-3 or WNT6 in T-47D cells." (PMID 34911552, 2021). "Treatment with WNT5A doubled the ratio of phosphorylated to un-phosphorylated PIK3CA, showing that this non-canonical WNT pathway also operates in MCF7 breast cancer cells." (PMID 32498332, 2020). "To assess the functional role of RHOU in this context we analyzed the highly aggressive basal-like breast cancer cell line MDA-MB-231, whose motility and invasivity have been shown to require the expression of the non-canonical WNT5a and WNT5b ligands." (PMID 30654518, 2019). "We prepared MCF-7, an ER-positive breast cancer cell line expressing no Wnt5a, and forced it to express Wnt5a constitutively (MCF-7/Wnt5a cells)." (PMID 29765514, 2018). "A similar negative impact on cell proliferation after Wnt5a silencing was observed in HT29 colon cancer cells and in MDA-MB231 breast cancer cells." (PMID 29453334, 2018). "In addition to its oncogenic roles in cancers, Wnt5a also has been found to inhibit canonical Wnt/β-catenin signaling in a Ror2-dependent manner and has a tumor suppressor role in several cancer types, such as colorectal cancer (CRC), thyroid cancer, and maybe breast cancers as well." (PMID 27895670, 2016). "However, another report identified that Wnt5a could induce invasiveness of cancer cells and the production of matrix metalloproteinase-7 (MMP7) and tumor necrosis factor-α (TNF-α) in macrophages, which was essential for macrophage-induced invasiveness in breast cancer." (PMID 27895670, 2016). "WNT5A, which signals through a non-canonical WNT pathway, is a candidate tumor suppressor in breast cancers." (PMID 24586797, 2014). "For example, CUX1 did not stimulate the expression of WNT5A in MCF10A cells, although this gene was upregulated in two MMTV-CUX1 mammary tumors and was previously reported to be activated by CUX1 in the PANC1 and HT1080 cell lines." (PMID 25217618, 2014). "However, it has been shown that the ability of WNT5A signaling to impair breast cancer cell migration and invasion is not related to a reversal of the EMT status of these cancer cells, thus defining the action of WNT5A as an EMT-independent mechanism." (PMID 30171384, 2018). "However, WNT5A-expressing MDA-MB-468 cells did not respond to extracellular lactate treatment, suggesting that WNT5A signaling abolishes the response of breast cancer cells towards extracellular lactate." (PMID 29069720, 2017). "Thus, to address this problem, we transfected two metastatic breast cancer cell lines (MDA-MB-468 and MDA-MB-231) with a WNT5A plasmid as these cells have no endogenous WNT5A expression." (PMID 29069720, 2017).
breast carcinoma (continued). "This study presented results on the involvement of Wnt5A and the subsequent activation of the non-canonical PKA/β-catenin pathway in chemoresistance in two drug-resistant cell lines and in biopsied samples from breast cancer patients." (PMID 25401518, 2014). "In this regard, Wnt5a was also found to modulate cell cycle progression and contributes to the chemoresistance in pancreatic cancer cells and regulates ABCB1 expression in multidrug-resistant breast cancer cells through activation of the noncanonical PKA/beta-catenin pathway." (PMID 27895670, 2016).
gastric cancer (99 papers, 2008 to 2026). A primary or metastatic malignant neoplasm involving the stomach. "In a previous study, we found that low expression of WNT5A in gastric cancer tissues was significantly associated with the invasion and metastasis of tumor cells, and poor prognosis." (PMID 37534256, 2023). "WNT5A was found to be highly expressed in tumor stromal fibroblast gastric cancer studies and was associated with poor prognosis." (PMID 36387067, 2022). "Of note, Frizzled7 and Wnt5a are highly expressed in gastric cancer and both are associated with poor outcomes." (PMID 35358569, 2022). "Wnt5A expression in gastric cancer patients is associated with more advanced stages of the tumor and a poor prognosis for the patient." (PMID 31248166, 2019). "In gastric cancer and ovarian carcinoma, increased level of Wnt5A protein was associated with high grade tumors and with decreased patient survival, yet in colon cancer and HCC high level of Wnt5A protein correlated with increased patient survival." (PMID 30814912, 2019). "WNT-5A expression is highly increased in gastric cancer and positively associates with tumor invasiveness, metastasis, and survival of the patients." (PMID 26514730, 2016). "By the FOX family member such as FOXL1, hedgehog signals can induce WNT5A upregulation, which is a cancer-associated gene involved in invasion and metastasis of gastric cancer." (PMID 27403158, 2016). "Clinically, we have identified that reduced Wnt5a expression are associated with poor differentiation stage of gastric cancer tissue." (PMID 25779663, 2015). "Previous analysis of the role of Wnt5a in gastric cancer cell lines indicated that loss of Wnt5a resulted in changes in the actin cytoskeleton." (PMID 23352643, 2013). "On the contrary, in non-small-cell lung cancer, Wnt5a overexpression was associated with short survival and in gastric cancer, increased Wnt5a protein expression correlated with advanced tumor stages and poor survival." (PMID 23342259, 2012). "DVL mediates the adhesion-related effects of Wnt5a in gastric cancer cells to regulate cytoskeleton dynamics, further enhancing cell motility and tumor progression." (PMID 39936971, 2025). "The coordinated regulation of miR-26a-5p and Wnt5a contributed to the inhibition of gastric cancer cell growth and the promotion of apoptosis." (PMID 41311720, 2025). "Helicobacter pylori infection can activate the WNT/β-catenin signaling pathway, inducing WNT5A expression, inflammation, and gastric cancer, as well as gastric stem cell generation and proliferation." (PMID 41440381, 2025). "In a gastric cancer model, GA exerted antitumor effects by upregulating miR-26a-5p and downregulating Wnt5a." (PMID 41311720, 2025). "While Wnt5a can act as a tumor suppressor in some contexts, its overexpression is correlated with aggressive tumor behavior in gastric cancer." (PMID 39936971, 2025). "miR-876–5p and miR-26a-5p can reduce the expression of WNT5A, inhibit the proliferation and migration of gastric cancer cells and induce apoptosis." (PMID 38952556, 2024). "TCGA database revealed high WNT5A expression in patients with stage IV gastric cancer compared with stage IA." (PMID 38240752, 2024). "A bioinformatic meta-analysis found that WNT5A is strongly expressed in 617 out of 1,034 gastric cancer patients." (PMID 39176352, 2024). "We analysed TCGA database and found that patients with gastric cancer at stage IV expressed higher WNT5A mRNA expression compared with that at stage I, which indicates that WNT5A contributes to poorer prognosis and metastasis in patients with gastric cancer." (PMID 38240752, 2024). "Here, we analyze the role of RUNX3 in gastric cancer cells and establish WNT5A as its downstream target in driving metastasis." (PMID 38240752, 2024). "A better understanding of RUNX3 regulation of WNT5A will yield insights to treatment of late-stage gastric cancer." (PMID 38240752, 2024).
gastric cancer (continued). "In particular, RUNX3 binds to the WNT5A gene and is required for strong WNT5A expression in the gastric cancer cell line HGC-27." (PMID 38240752, 2024). "In 2016, Bone marrow-derived mesenchymal stem cells (BM-MSCs), important components of the TME, have been shown to promote the proliferation of gastric cancer cells through Wnt5a-Ror2 pathway." (PMID 38952556, 2024). "The report that anti-WNT5A antibody inhibited the cell migration of gastric cancer cells further supports our findings." (PMID 38240752, 2024). "We next examine the coexpression of RUNX3 and WNT5A in E-cadherin positive gastric cancer cells in the human specimens (n = 35)." (PMID 38240752, 2024). "This unexpected intercellular signaling mechanism of receptor transfer provides insights and a possible explanation of how gastric cancer cells respond to high WNT5A in their environment." (PMID 37722040, 2023). "Lymph node metastasis-derived gastric cancer cells specifically educate MSCs through exosomal Wnt5a-mediated activation of YAP signaling." (PMID 37865637, 2023). "In gastric cancer, WNT5A is highly expressed in the stroma, contributes to the tumor microenvironment, and is explicitly up-regulated in cancer-associated fibroblasts (CAFs) compared to fibroblasts isolated from the normal gastric stroma." (PMID 37722040, 2023). "In support of our data, enhanced levels of WNT5A facilitate cell migration and invasion of gastric cancer cells." (PMID 37722040, 2023). "The crucial PCP ligand in this context is WNT5A, which is produced by the CAFs, and gastric cancer cells react upon this signal by enhanced polarized migration." (PMID 37722040, 2023). "Here, we show that these cancer-associated fibroblasts provide both the signaling protein WNT5A and its receptor ROR2 to gastric cancer." (PMID 37722040, 2023). "Inhibiting Wnt5a blocked fibroblast-induced gastric cancer cell proliferation and migration in vitro, and metastasis of gastric cancers in vivo." (PMID 35358569, 2022). "Wnt5a functions as a supportive niche factor in gastric cancer, where it is upregulated by the tumor microenvironment." (PMID 35358569, 2022). "Overexpression of miR-26a-5p can suppress the Wnt5a expression, thereby promoting programmed cell death and inhibiting the malignant capabilities of gastric cancer cells." (PMID 36262998, 2022). "In gastric carcinoma, microenvironmental lymphocytes secrete Wnt5a to stimulate the proliferation of malignant cells by activating RhoA." (PMID 35210425, 2022). "For example, WNT5A is overexpressed in gastric cancer where it positively correlates with the presence of lymph node metastasis, tumor depth, EMT induction, and poor prognosis." (PMID 34702444, 2021). "Wnt5a-enriched exosomes isolated from lymph node metastasis-derived gastric cancer (LNM-GC) cells induced YAP dephosphorylation in bone marrow-derived mesenchymal stem cells (BM-MSCs)." (PMID 34283059, 2021). "For example, berberine has been shown to inhibit proliferation, migration, and invasion by targeting the AMPK/HNF4α/WNT5A pathway in gastric cancer cells." (PMID 33231372, 2021). "In another report, Wnt5a promoted cell migration via the PI3K/AKT/GSK3b/RhoA signaling pathway in gastric cancer." (PMID 34794402, 2021). "In summary, the evidence analyzed in this review suggests that Wnt5a plays a significant role in gastric cancer." (PMID 32195251, 2020). "WNT5A also induced gastric cancer migration and invasion by binding to FZD2 and ROR2, and treatment in vivo with anti-WNT5A antibody inhibited liver metastasis of gastric cancer cells." (PMID 33178184, 2020). "Wnt5a is increased in gastric cancer samples; however, most gastric cancer cell lines seem to exhibit little expression of this ligand, thus raising the question about the source of this ligand in vivo." (PMID 32195251, 2020). "Apart from Wnt5A, also other Wnts such as Wnt1, Wnt2B, Wnt6 and Wnt10A have been found to be enhanced in gastric cancer tissue." (PMID 31248166, 2019).